APP (amyloid beta precursor protein)
Diseases named in the same sentence as APP in open-access papers (continued):
Sharing a sentence is not in itself a finding about the gene and the disease.
Alzheimer disease (continued). "Alzheimer’s disease is linked to several genetic mutations, including amyloid precursor protein (APP) and presenilin genes (PSEN1 and PSEN2) mutations that have been found to be the most common, leading to early-onset Alzheimer’s disease." (PMID 41007636, 2025). "Alzheimer’s disease is mainly associated with amyloid plaque deposition and microglial cells play a key role in amyloid protein processing (APP) and dysregulation of it causes plaque deposition." (PMID 40893157, 2025). "The APP gene encodes the amyloid precursor protein that forms amyloid plaques, a hallmark of Alzheimer’s disease." (PMID 40177266, 2025). "At least 40 APP mutations are documented as being linked to Alzheimer’s disease, with their impact on APP processing and Alzheimer’s disease development showing variation." (PMID 40426657, 2025). "Our genetic investigation revealed a single-nucleotide polymorphism (SNP) (rs2154481-C) in the APP locus associated with protective effects on Alzheimer’s disease (OR = 0.95, P = 1 × 10−11)." (PMID 40867848, 2025). "PSEN1, PSEN2, and APP mutations cause Alzheimer’s disease (AD) with an early age at onset (AAO) and progressive cognitive decline." (PMID 39754192, 2025). "APP is a transmembrane protein implicated in Alzheimer’s disease (AD) and cerebral amyloid angiopathy." (PMID 41441335, 2025). "A rare form of Alzheimer's disease (AD) is genetically determined through autosomal dominant mutations in the APP, PSEN1, or PSEN2 genes." (PMID 40110659, 2025). "Excessive manganese (Mn) exposure causes cognitive deficits similar to Alzheimer’s disease (AD) by affecting amyloid precursor protein (APP) and its processing." (PMID 40278152, 2025). "To validate this model, we cultured Alzheimer’s disease (AD) forebrain cortical populations derived from human iPSCs carrying APP (amyloid precursor protein) mutations (K670M/N671L + V717F)." (PMID 40150709, 2025). "Serotonergic System: Dysregulation of serotonin (5-HT) signaling is implicated in Alzheimer’s disease (AD), affecting amyloid precursor protein (APP) processing and Aβ deposition." (PMID 40821767, 2025). "This study evaluates the efficacy of APP ASOs in astrocytes derived from an individual with Down syndrome (DS), a population at high risk for Alzheimer's disease (AD)." (PMID 39877983, 2025). "A hallmark of Alzheimer’s disease (AD) is the dysregulated metabolism of amyloid beta (Aβ), a peptide produced through the cleavage of amyloid precursor protein (APP) by enzymes, including β-secretases." (PMID 40243482, 2025). "Individuals with DS carry a high risk for dementia caused by Alzheimer's disease (AD), due to the triplication of chromosome 21, which leads to the overexpression of the amyloid precursor protein (APP) and amyloid deposition in brain." (PMID 41416575, 2025). "PICALM is a genetic risk factor for late-onset Alzheimer’s disease that participates in amyloid-β transcytosis and processing of amyloid precursor protein (APP)." (PMID 38594674, 2024). "Another factor strengthening cholesterol’s causative correlative nature to Alzheimer’s disease is found in a link between cholesterol levels and amyloid precursor protein (APP) metabolism." (PMID 38572181, 2024). "APP/PS1 mice are double transgenic Alzheimer's disease (AD) model mice expressing human APP and presenilin 1 with familial mutations causing early disease onset." (PMID 38915938, 2024). "Among the reported rG4 sequences in humans, the amyloid precursor protein (APP) rG4 is one of the most studied due to the importance of the APP gene's association with Alzheimer’s disease." (PMID 39558155, 2024). "A new study revealed that ELAVL4 influences multiple biological pathways linked to Alzheimer’s disease, including those involved in synaptic function and the expression of genes downstream of APP and tau signaling." (PMID 38632655, 2024).
Alzheimer disease (continued). "Over-expression of the target protein amyloid precursor protein (APP) gene caused by exon variants of NDUFAF7 is associated with the risk of Alzheimer’s disease." (PMID 38783263, 2024). "IDE also plays a significant role in the degradation and clearance of amyloidogenic peptides derived from APP secreted by neurons and microglia, and a deficiency in the function of this protein is associated with Alzheimer’s disease." (PMID 39456746, 2024). "APPtg mice overexpress human APP with two mutations, Swedish and Indiana, linked to familial Alzheimer’s disease." (PMID 38464180, 2024). "NEU1 is strongly implicated in Alzheimer’s disease (AD) pathogenesis, where it regulates amyloid precursor protein (APP) metabolism through desialylation." (PMID 39194692, 2024). "The depletion of any of these enzymes elevates Hcy-thiolactone and N-Hcy-protein, which dysregulate the Phf8 → H4K20me1 → mTOR → autophagy pathway and upregulate APP, causing Aβ accumulation, a hallmark of Alzheimer’s disease." (PMID 39125665, 2024). "Amyloid precursor protein (APP) is primarily associated with Alzheimer’s disease and the accumulation of amyloid plaques in the brain." (PMID 38167131, 2024). "APP is a precursor to the toxic amyloid beta protein which eventually forms the amyloid plaques associated with Alzheimer’s disease." (PMID 38977662, 2024). "APBA1 encodes a neuronal adaptor protein that interacts with amyloid precursor protein, encoded by the Alzheimer disease-associated APP gene." (PMID 38575728, 2024). "Familial Alzheimer’s disease typically appears earlier in life and is caused by hereditary genetic mutations in amyloid precursor protein (APP), presenilin 1 (PSEN1), and presenilin 2 (PSEN2)." (PMID 38410184, 2024). "Treadmill exercise ameliorated Alzheimer’s disease-associated cognitive dysfunction, amyloid plaque pathology, Tau hyperphosphorylation, and ubiquitin–proteasome system dysfunction in APP/PS1 transgenic mice." (PMID 38347638, 2024). "Familial Alzheimer's disease (fAD) is caused by autosomal dominantly inherited mutations in the amyloid precursor protein (APP) and presenilin 1 or 2 (PSEN1/2) genes." (PMID 38824433, 2024). "The specific amino acid substitutions are at positions 235 and 236 in the arginine/glycine/glycine (RGG)-rich domain of the FUS gene, which resembles the so-called Swedish mutation (K595N/M596L) in APP in Alzheimer’s disease." (PMID 38872230, 2024). "Although Alzheimer’s disease arises predominantly as a sporadic condition of late adult life, there are rarer early-onset Mendelian forms caused by mutations in the APP gene or in genes (PSEN1 and PSEN2) known to alter its enzymatic cleavage." (PMID 38287166, 2024). "Upstream variants in promoter elements of the amyloid precursor protein (APP) gene lead to altered binding behavior of transcription factors and are associated with Alzheimer’s disease." (PMID 39596509, 2024). "Activation of NLRP3-containing inflammasome, which is responsible for IL-1β maturation, has been shown to contribute to Alzheimer’s disease (AD)-associated pathogenesis in both APP- and tau-transgenic mice." (PMID 39539344, 2024). "We identified ligand-receptor pairs in three independent datasets and found involvement of the Alzheimer's disease risk genes APP and APOE across datasets." (PMID 38849813, 2024). "Herein, we investigate the molecular requirements of thiophene‐vinyl‐benzothiazole based ligands to detect a specific type of Aβ deposits found in individuals with dominantly inherited Alzheimer's disease caused by the Arctic APP E693G mutation." (PMID 39508558, 2024). "Just as measuring Amyloid Precursor Protein (APP) levels in platelets can serve as a diagnostic tool for assessing Alzheimer’s disease severity, it is reasonable to consider protein levels as biomarkers for future complications." (PMID 39337488, 2024).
Alzheimer disease (continued). "The Alzheimer's disease (AD) central gene, amyloid precursor protein (APP), has shown contrasting transcript variant dynamics in various cell types." (PMID 38802572, 2024). "Although APP is predominantly linked to the pathophysiology of Alzheimer’s disease, a recent report pointed out its association with obesity phenotypes such as insulin resistance and inflammation, which are regulated by tumor necrosis factor α (TNF-α)." (PMID 39329749, 2024). "Familial Alzheimer’s disease cases reveal mutations in the amyloid precursor protein (APP) and presenilins (PSEN1 and PSEN2) involved in Aβ processing." (PMID 39408635, 2024). "Alzheimer’s disease animal model with T deficiency was performed by castration to 3-month-old male APP/PS1 mice." (PMID 38752208, 2024). "Alzheimer’s disease encompasses both sporadic and familial forms, with genetic mutations in genes like amyloid precursor protein (APP) and presenilins (PSEN1 and PSEN2) implicated in family cases." (PMID 38891938, 2024). "The increased APP gene dose due to its triplication in Down syndrome is the leading cause of Alzheimer’s disease in Down syndrome and is also associated with oxidative stress." (PMID 38540156, 2024). "Secondly, LMTK1 is involved in the endosomal transport of amyloid precursor protein (APP), a key axonal transport cargo in Alzheimer’s disease and whose mutations cause some familial forms of the disease." (PMID 39520508, 2024). "Another research group found that MT5-MMP cleaves APP in response to oxidative stress further linking MT5-MMP to potentially pathogenic pathways in Alzheimer’s disease." (PMID 38992438, 2024). "The Down syndrome (DS) population is genetically predisposed to develop Alzheimer’s disease (AD) in part due to the triplication of chromosome 21 and the resulting increase in amyloid precursor protein (APP)." (PMID 37641577, 2024). "Mitochondria dysfunctions and mitophagy failure have been associated with several Alzheimer’s disease (AD) related molecular actors including amyloid beta (Aβ) and recently the amyloid precursor protein-C terminal fragments (APP-CTFs)." (PMID 38806484, 2024). "Familial Alzheimer’s disease (fAD) is a rare, inherited form of AD often linked to mutations in the APP and presenilin 1 (PSEN1) and presenilin 2 (PSEN2) genes." (PMID 39684324, 2024). "Down syndrome (DS) is strongly associated with Alzheimer’s disease (AD), attributable to APP overexpression." (PMID 39070643, 2024). "Autophagy is also thought to play roles in the metabolism of disease-related proteins, including amyloid precursor protein (APP), which is associated with Alzheimer’s disease (AD)." (PMID 39080084, 2024). "Alzheimer's disease (AD) is associated with brain accumulation of synaptotoxic amyloid-β (Aβ) peptides produced by the proteolytic processing of amyloid precursor protein (APP)." (PMID 38331575, 2024). "Then, we illustrate its applicability by creating an APP-TGCN on The Religious Orders Study and Memory and Aging Project dataset, aiming to identify the molecular pathways specifically associated with APP role in Alzheimer’s disease." (PMID 39030261, 2024). "SORL1 (1.36-fold) encodes for a sorting protein-related receptor that is downregulated in Alzheimer’s disease (AD) and is implicated in the trafficking and processing of amyloid precursor protein (APP)." (PMID 39335533, 2024). "The hallmark of Alzheimer’s disease (AD) is the buildup of amyloid-β (Aβ), which is produced when the amyloid precursor protein (APP) misfolds and deposits as neurotoxic plaques in the brain." (PMID 39770511, 2024). "The second most central node was APP (the amyloid beta precursor protein), implicated in patients with Alzheimer’s disease (AD) and also in glaucomatous neurodegeneration." (PMID 39458974, 2024). "The normal function of amyloid precursor protein (APP) implicated in Alzheimer’s disease is unclear." (PMID 37923712, 2023).
Alzheimer disease (continued). "While some animal models, such as those with APP mutations, have yielded promising results, a more comprehensive assessment encompassing various types of KD and diverse rodent models of Alzheimer’s disease is crucial." (PMID 38248828, 2023). "NUMB has also been linked to Alzheimer’s disease, where it plays a role as an adaptor of amyloid precursor protein (APP), an essential protein in the pathogenesis of the disease." (PMID 36672267, 2023). "Familial Alzheimer’s disease (FAD) mutations have been identified in APP and PS1, with most being found in PS1 (>150 have been reported in PS1 to date)." (PMID 36835396, 2023). "Alzheimer’s disease is caused by the accumulation of extracellular plaques composed of Amyloidß (Aß) peptides, derived from the mis-processing of the Amyloid Precursor Protein (APP)." (PMID 37733679, 2023). "Neuronal iron export occurs via a transmembrane ion channel, ferroportin, and the Alzheimer’s disease (AD)-implicated amyloid precursor protein (APP) stabilizes ferroportin expression on the membrane to promote iron efflux." (PMID 36674772, 2023). "For example, the amyloid-beta precursor protein (APP) gene-encoded amyloid protein level is associated with early-onset Alzheimer’s disease (AD), which has been characterized in DS patients." (PMID 38095646, 2023). "Although APP is an Alzheimer’s disease-associated protein, it is also reportedly overexpressed in nasopharyngeal, colon, and pancreatic cancers." (PMID 37905960, 2023). "In Alzheimer’s disease (AD), both tau and amyloid precursor protein (APP), associated metabolites and secretase enzymes have been shown to be present in exosomes." (PMID 39698299, 2023). "Aβ peptides derived from the amyloid precursor protein (APP) have been strongly implicated in the pathogenesis of Alzheimer’s disease." (PMID 37923712, 2023). "Four genes have been identified to be associated with Alzheimer’s disease, namely, the amyloid precursor protein (APP) gene, the presenilin 1 (PSEN1) gene, the presenilin 2 (PSEN2) gene and the apolipoprotein E (ApoE) gene." (PMID 37362440, 2023). "APP misprocessing and accumulation within the endo-lysosomal network is a crucial hallmark of Alzheimer’s disease, and is sufficient to induce lysosomal dysfunction." (PMID 37248224, 2023). "Familial early-onset Alzheimer’s disease (FEOAD) or early-onset AD (EOAD) associated with dominant mutations in APP, PSEN1 and PSEN2 have a high penetrance for displaying many of the clinical symptoms associated with AD." (PMID 36834781, 2023). "In Alzheimer’s disease, the accumulation of proteins such as tau and APP into plaques is believed to be partly caused by changes in proline isomerization." (PMID 37508437, 2023). "Another preclinical study found that when administered even at a late stage of Alzheimer’s disease-related pathology, butyrate supplementation improved associative memory in APP/PS1-21 mice." (PMID 37179659, 2023). "In Alzheimer’s disease (AD), a neurodegenerative disorder characterized by deficient cognitive processes and the accumulation of amyloid precursor protein (APP) and amyloid-β, LRP6 mutations are considered to be pathogenic factors." (PMID 37139333, 2023). "Individuals with DS have a higher risk of Alzheimer’s disease because patients have an extra copy of the amyloid precursor protein (APP) gene located on chromosome 21, which is trivalent in this population." (PMID 37238612, 2023). "It has several types, with the early-onset variant presenting usually as a result of a genetic mutation in Alzheimer’s disease susceptibility genes, such as amyloid precursor protein (APP) or presenilin 1/2 (PSEN1/2)." (PMID 37834345, 2023). "The aspartate protease γ-secretase cleaves the transmembrane domain (TMD) of C99, a shedded form of the amyloid precursor protein (APP) being causally linked to Alzheimer’s disease." (PMID 36792683, 2023).
Alzheimer disease (continued). "Amyloid precursor protein (APP) has been widely studied due to its association with Alzheimer’s disease (AD)." (PMID 37834082, 2023). "Alzheimer’s disease is associated with aberrant APP processing in neurons with an over-abundance of Aβ linked to disease pathology." (PMID 37108327, 2023). "The concept of loss of APP function contributing to Alzheimer’s disease has been supported by some studies demonstrating decreased APP transcript or protein levels in patient brains or CSF76–78." (PMID 37923712, 2023). "The functions of the amyloid precursor protein APP go beyond its widely recognized association with Alzheimer’s disease." (PMID 37601107, 2023). "Approximately 25 pathogenic variants in the APP gene have been associated to the etiology of Alzheimer’s disease." (PMID 37784196, 2023). "The etiology of early-onset Alzheimer’s disease (EOAD) is associated with alterations in the production of amyloid beta (Aβ) species caused by mutations in the APP, PSEN1, and PSEN2 genes." (PMID 37108607, 2023). "In 1991, Hardy’s group has uncovered the first mutation of the APP gene which, they expected, would be responsible for the occurrence of the familiar Alzheimer’s disease." (PMID 37693644, 2023). "For example, the Alzheimer Disease (AD)-associated proteins APP, BACE1, Nicastrin, Tau, APOE and TREM2 all have several N- and O-glycosylations." (PMID 37201132, 2023). "For example, the Drosophila gene amyloid precursor protein-like (Appl) gene encodes a protein product (APPL) that is orthologous to the human amyloid beta precursor protein (APP) associated with Alzheimer’s disease." (PMID 35092497, 2023). "A small proportion of patients with Alzheimer’s disease (AD) carry autosomal-dominant mutations in the APP, PSEN1, or PSEN2 genes (adAD)." (PMID 37131241, 2023). "For example, mouse models for Alzheimer’s disease (AD) over-express specific mutations [e.g., in the amyloid precursor protein (APP) and presenilins (PS)] that are known to induce early-onset familial cases of AD." (PMID 36896346, 2023). "Although most cases of Alzheimer’s disease have a sporadic onset, familial Alzheimer’s disease is mainly caused by mutations in three genes: APP, presenilin 1 (PSEN1), and presenilin 2 (PSEN2)." (PMID 36672267, 2023). "It would be of interest to determine the effect of Alzheimer’s disease promoting and protective mutations in APP on TGFβ activation and proteostasis in mammalian neurons." (PMID 37923712, 2023). "Mutations in the genes encoding amyloid precursor protein (APP), presenilin 1 (PS1), and presenilin 2 (PS2) proteins affect amyloid beta (Aβ) generation, leading to altered APP cleavage and the pathophysiology underlying Alzheimer’s disease (AD) progression." (PMID 37108607, 2023). "In this study, we systematically explored the relationship between Alzheimer's disease (AD) and non‐pathogenic variants of APP, PSEN1, and PSEN2 in a total of 3557 individuals in a Chinese population." (PMID 36217304, 2023). "Familial forms of Alzheimer’s disease representing 5% of the patients are associated to different type of APP gene mutations." (PMID 36898995, 2023). "Autophagic vacuole-associated BACE1 is accumulated in the distal axon of Alzheimer’s disease-related mutant human APP transgenic neurons and mouse brains which exacerbates the AD pathological changes." (PMID 37240832, 2023). "The interaction between APP and Arc is of interest because several studies have implicated Arc in control of β-amyloid accumulation and Alzheimer’s disease (AD)." (PMID 37326306, 2023). "All known genetic causes of Alzheimer’s disease (AD) are related to the abnormal processing of the amyloid precursor protein (APP) and subsequent pathological accumulation of Aβ peptides in the brain." (PMID 37047093, 2023). "Proteins associated with the enriched KEGG pathway ‘Alzheimer’s disease’ were of interest given the role of APP in the pathology of the disease, namely the source of neurotoxic peptide Aβ." (PMID 37108327, 2023).